CD274 (CD274 molecule)
Diseases named in the same sentence as CD274 in open-access papers (continued):
Sharing a sentence is not in itself a finding about the gene and the disease.
colorectal cancer (continued). "Interestingly, the co‐transcription between STAT3 and STAT4 has been reported in colorectal carcinoma, but whether STAT4 indirectly transactivates CD274 (coding PD‐L1) through synergistic effect with STAT3 remains unknown." (PMID 38107057, 2023). "Although tumor CD274 (PD‐L1) overexpression does not appear to have a prognostic role in colorectal carcinoma, our previous study indicates that tumor CD274 overexpression may serve as a predictive biomarker for tumor resistance to aspirin use after colorectal cancer diagnosis." (PMID 37538192, 2023). "Finally, the immune checkpoints PDCD1 (PD-1) and CD274 (PDL-1) were also positively correlated with interleukin-17A mRNA expression, indicating that interleukin-17A is a promising predictor of the immunotherapeutic outcome of PD-1/PDL-1 blockade in colorectal cancer." (PMID 36098359, 2022). "Furthermore, using the CPTAC cohort, we confirmed a negative correlation between GALNT7 protein levels and CD274 expression, specifically in MSI colorectal cancers." (PMID 40824763, 2025).
hepatocellular carcinoma (914 papers, 2011 to 2026). A malignant tumor that arises from hepatocytes. "Interleukin (Il) 10, Il6 or Cd274 (PD-L1) can basically be expressed by hepatoma cells, cancer-associated fibroblasts, TAMs or MDSCs, which promote tumour growth, metastasis and immune evasion." (PMID 34830835, 2021). "Other epigenetics enzymes, such as the histone methyltransferase, EZH2, have been shown to regulate the expression of PD-L1 in hepatocellular carcinoma by upregulating H3K27me3 levels on the promoters of CD274 (encoding PD-L1) and IRF1." (PMID 32316916, 2020). "Notably, a recent study suggested that enhancer of zeste homolog 2 (EZH2) can suppress PD-L1 expression by directly upregulating H3K27me3 levels at CD274 (encoding PD-L1) promoter regions in hepatoma cells." (PMID 33324209, 2020). "In the present study, we provided evidence that spermine exerts an immunosuppressive role through enhancing the expression and glycosylation of programmed cell death ligand 1 (PD-L1, encoded by the CD274 gene) in hepatocellular carcinoma." (PMID 36348350, 2022). "Analysis using the Xiantao online tools revealed that the CD274 (PD-L1) gene exhibits high expression levels in tumor samples from hepatocellular carcinoma, pancreatic cancer, renal cancer, and urothelial cancer, alongside elevated expression of αv (ITGAV) and β3 (ITGB3) genes." (PMID 41601637, 2026). "However, in hepatocellular carcinoma cells, EZH2 enhances H3K27me3 at the promoters of CD274, which encodes PD-L1, and interferon regulatory factor 1 (IRF1), leading to an inverse correlation by inhibiting PD-L1 expression." (PMID 40308579, 2025). "The authors proposed that EZH2 suppresses PD-L1 expression via epigenetic modification, by upregulating H3K27me3 levels at the CD274 (which encodes PD-L1) and IRF1 gene in hepatoma cells, highlighting the critical role of EZH2 in reshaping the tumour immune microenvironment." (PMID 40310411, 2025). "In addition, TUBA1B has been shown to mediate the infiltration of several immune cells in hepatocellular carcinoma, including CD274 and CTLA4." (PMID 36140469, 2022). "A recent study found that EZH2, in hepatoma cells, can suppress PD-L1 expression by directly upregulating H3K27me3 levels on the promoters of CD274, which encodes PD-L1 and interferon regulatory factor 1 (IRF1), an essential transcription factor for PD-L1 expression." (PMID 32708698, 2020). "The expression of PD-L1 was suppressed by epigenetic modificator EZH2 via directly upregulating the promoter H3K27me3 levels of CD274 and IRF1 in hepatoma cells." (PMID 37056572, 2023). "A recent study showed that high expression of PFKFB3 induces CD274 molecule (CD274) expression via activating the NF-κB signal pathway in monocytes, therefore inhibiting CD8+ T cell activity and poor prognosis in hepatocellular carcinoma patients." (PMID 37253634, 2023). "In hepatocellular carcinoma, it was identified that two elements (IRE1/2) in the 5′-flanking region of the CD274 promoter were the binding sites of IRF-1, which participated in regulating PD-L1 transcription." (PMID 33413496, 2021). "For example, EZH2 methyltransferase activity in hepatocellular carcinoma cells caused H3K27me3 histone modification near IRF1 and CD274 promoter regions, which suppressed their expression without affecting the IFNγ/STAT1 signaling pathway." (PMID 38396830, 2024). "However, our BSP analysis in hepatoma cells with low constitutive expression of PD-L1 showed almost no methylation on the CD274 promoter regions that were predicted to be CpG islands." (PMID 31727135, 2019). "Similarly, liver-specific knockout of Gpx4 accelerates diethylnitrosamine-induced hepatocellular carcinoma by releasing high-mobility group box 1 (HMGB1), recruiting myeloid-derived suppressor cells (MDSCs), and upregulating the checkpoint protein CD274 (also known as PD-L1)." (PMID 38844964, 2024).
hepatocellular carcinoma (continued). "Moreover, in hepatocellular carcinoma and PCa, a negative correlation between EZH2 and PD-L1 was reported, which may result from the upregulation of H3K27me3 levels in the promoters of CD274 and IRF1." (PMID 36135315, 2022).
ovarian carcinoma (779 papers, 2005 to 2026). A malignant neoplasm originating from the surface ovarian epithelium. "The PD-L1 protein was encoded by the CD274 gene and is expressed in several types of tumor cells, such as ovarian cancer and HCC." (PMID 37408047, 2023). "In line with the sequencing data, our investigation discovered that ginger inhibited the expression of CLDN7, CLDN11, and CD274 in ovarian cancer cells SKOV3." (PMID 38575994, 2024). "The expression of CD274 in tumor cells is regarded as prognostic in many types of human malignancies such as colon cancer and ovarian cancer." (PMID 38347589, 2024). "BRD4 is known to be a critical regulator of PD-L1 expression in tumor cells, dendritic cells and macrophages by directly binding the CD274 (encoding PD-L1) gene promoter, at least in ovarian carcinoma cell-lines." (PMID 35226658, 2022). "Recently, immune-checkpoint inhibitor (ICI) targeting programmed death-1 (PD-1) and programmed death ligand-1 [PD-L1 (CD274)] have been investigated in ovarian cancer, but the clinical response of these inhibitors is quite limited." (PMID 35991556, 2022). "A more recent study reveals that in ARID1A deficiency ovarian cancer, HDAC6 inhibition synergizes with anti-PD-L1 immune checkpoint blockade, and ARID1A directly repressed the transcription of the CD274 (encoding PD-L1) gene." (PMID 34671561, 2021). "When ovarian cancer cells were co-incubated with platelets for 24 h, EpCAM mRNA expression decreased (P = 0.0404) while the mRNA expression of the immune checkpoint marker PD-L1 (CD274) increased (P = 0.0174) in cells cloaked with platelets." (PMID 41125825, 2026). "However, consistent with previous findings in ovarian cancer cell lines showing induction of PD-L1 expression by PARPis, CD274 expression increased after rucaparib run-in in three of five responders but not in non-responders." (PMID 38971950, 2024). "Finally, the significance test indicated that the expression pattern of the CD274 gene has significant differences when ovarian cancer patients were stratified by stage (rank test P < 0.05)." (PMID 36157232, 2022). "Programmed death-ligand 1 (PD-L1), also known as CD274, is high expressed in ovarian cancer." (PMID 34616622, 2021). "Drug-resistant ovarian cancer cells exhibit repression of OX-40 L and 4-1BBL (immune-stimulatory molecules), with concomitant augmented expression of immunosuppressive molecules PD-L1/CD274." (PMID 30064416, 2018). "Therefore, by altering the m6A methylation levels of CLDN7, CLDN11, and CD274, which in turn affects the multiplication of ovarian cancer cells SKOV3 may be one of the mechanisms by which ginger is anti-SKOV3." (PMID 38575994, 2024). "We also found a significant positive correlation between PD-L1 (CD274) and the PDCD1LG2, BIRC3, RELB, and VSIR genes in the TCGA ovarian cancer-patient database." (PMID 39996786, 2025). "Ginger inhibits ovarian cancer cells’ SKOV3 invasion by regulating m6A methylation through CLDN7, CLDN11, and CD274." (PMID 38575994, 2024). "The outcomes demonstrated that in ovarian cancer cells SKOV3, CLDN7, CLND11, and CD274 were reduced in the Ginger-treated group than in that of the Con group." (PMID 38575994, 2024). "Our qRT-PCR analysis revealed a negative correlation between SNRPE expression and the expression of CD274 and CD8A in ovarian cancer tissues." (PMID 37090728, 2023). "BRD4 directly targets CD274 since the ChIP-seq assay revealed a positive correlation between CD274 promoter and BRD4 in ovarian cancer." (PMID 34088360, 2021). "The analysis of TCGA datasets of ovarian cancer indicated a negative correlation between SETDB1 or TRIM28 and CD274 expression (encoding PD-L1 immune checkpoint)." (PMID 39519018, 2024). "We next observed that SPP1 expression was positively related with immune-checkpoint, such as CD274, CTLA-4, LAG3 and TIGIT, suggesting that SPP1 may play an important role in immune tolerance of ovarian cancer." (PMID 36585688, 2022).
ovarian carcinoma (continued). "Therefore, altering the m6A methylation levels of CLDN7, CLDN11, and CD274, which in turn affects the growth of SKOV3 in ovarian cancer cells may be one of the mechanisms by which ginger resists ovarian cancer cells SKOV3." (PMID 38575994, 2024).
glioma (759 papers, 2010 to 2026). A benign or malignant brain and spinal cord tumor that arises from glial cells (astrocytes, oligodendrocytes, ependymal cells). "CD274 (PD-L1) is not only associated with decreased cytotoxic T lymphocytes and increased Tregs in glioma lesions, but also has an intrinsic oncogenic effect through interaction with Ras (10.3389/fphar.2018.01503)." (PMID 37351101, 2023). "Recent research revealed that the expression of CD274 induced under hypoxia condition was signally associated with poor survival in glioma patients." (PMID 36437961, 2022). "Gliomas of TrMRS high-risk group presented with significantly higher expression level of CD274 (PD-L1), CD276 (B7H3), HAVCR2 (TIM3), PD1 (CD279, PDCD1), and CD44." (PMID 36386216, 2022). "In this study, we provide more evidence to support the finding that the regulation of PD-L1 also known as cluster of differentiation 274 (CD274) glioma expression is directly associated with tumor IDH1 mutation status." (PMID 29643764, 2018). "Notably, we also found that 6 immune checkpoints were significantly upregulated in the high-glioma-risk group, including CD274, CTLA4, LAG3, LGALS9, PDCD1, and PDCD1LG2." (PMID 39465792, 2024). "Among them, most of the HLA, checkpoints, chemokines, costimulatory molecules, IFNG, CD8, and CD274 were highly expressed in the high-risk group, which showed that the high-risk group may get more chances from the anti-glioma immunotherapy." (PMID 36466844, 2022). "PTEN deficiency and activation of phosphatidylinositol-3-OH kinase (PI3K) could aggravate CD274 expression and weaken the function of tumor-associated T cells in gliomas." (PMID 34100771, 2021). "Furthermore, expression of regulators of mt-rRNA modification was associated with major moieties associated with immune checkpoints in glioma, especially PD-L1, PD-1, CD80, CD274, TIM3, and IDO1." (PMID 34566979, 2021). "In murine gliomas at the asymptotic phase, MDMs upregulated Il-1b that encodes an inflammatory cytokine, along with genes encoding inflammatory cytokine inhibitors Il1rn and Il18, and there was a subset with a high expression of the Cd274 mRNA encoding an immune-checkpoint inhibitor (PD-L1)." (PMID 33809675, 2021). "Correlation analysis revealed that the expression levels of CD48, CD276, and CD274 proteins in glioma were significantly correlated with their mRNA levels (r > 0.6, p < 0.05)." (PMID 40606983, 2025). "Upon treatment with mIDH1 inhibitors, mIDH1 glioma cells exhibit reduced DNA methylation in the CD274 regulatory region." (PMID 40927709, 2025). "Their analyses showed that IDH‐mutant glioma has lower expression of PD‐L1 (CD274) in comparison to IDH‐wildtype, across all grades, with significant adjusted P‐value of < 0.05 for grade IV (both CGGA and TCGA), and grade III (TCGA)." (PMID 38339779, 2024). "After that, we found that 6 immune checkpoints (CD274, CTLA4, LAG3, LGALS9, PDCD1, and PDCD1LG2) were significantly upregulated in the high-glioma-risk group, while RDH5, RDH10 and DHRS3 simultaneously have a substantial positive connection with PDCD1LG2." (PMID 39465792, 2024). "In general, gliomas had lower transcript expression of SIRPA (gene encoding SIRPalpha) and higher of PD-L1 (CD274), PD-L2 (PDCD1LG2), TIM-3 (HAVCR2), PD-1 (PDCD1) (respectively)." (PMID 36768201, 2023). "They noted subpopulations of monocytes/macrophages in mice expressing high levels of CD274 and suggested that these cells play an immunoregulatory role in gliomas microenvironment." (PMID 36768201, 2023). "The combined inhibition of IDO1, CTLA4, and CD274 (an immunosuppressive molecule best known as PD-L1) has been shown to mediate superior therapeutic effects against well-established gliomas in mice and induce the antitumor immune responses." (PMID 37342333, 2023). "Their mRNA expression levels and correlations with CD274 were validated with glioma cell lines using quantitative real-time PCR (qRT-PCR)." (PMID 37629061, 2023).
glioma (continued). "The DNA methylation levels in the regulatory regions of CD274 decrease when mIDH1 glioma cells are treated with an mIDH1 inhibitor." (PMID 36647827, 2023). "All six of the most critical ICGs that were examined, including CD274, CTLA4, HAVCR2, IDO1, PDCD1, and PDCD1LG2, exhibited a significant positive correlation with the risk scores in glioma samples." (PMID 36845382, 2023). "Based on TCGA and CGGA datasets, the importance of CD274 expression in glioma cells in infiltration of macrophades has been suggested." (PMID 36768201, 2023). "The highest expression was detected in the WHO glioma grade IV tumors (CD274 p = 2.0e − 08, HAVCR2 p = 1.5e − 09, LAG3 p = 9.7e − 05, PDCD1 p = 5.6e − 05, PDCD1LG2 p = 2.2e − 18, and SIGLEC15 p = 4.3e − 05)." (PMID 35198632, 2022). "ALKBH5 expression showed positive association with ICP receptors such as TNFRSF14, CD40, CD96 and CD200R1, and ICP ligands such as PDCD1LG2, CD70, TNFSF14, ICOSLG and CD274 in glioma tissues." (PMID 35444654, 2022). "For example, the checkpoint molecule CD274 can suppress the immune response against gliomas, and the expression of PD‐1 on T cells can bind to CD274 on gliomas, which can inhibit the activity of T cells and mediate immune escape." (PMID 35855654, 2022). "The efficacy of anti-PD1 immunotherapy in glioma patients can be influenced by the tumor mutation burden (TMB), PD-L1 (CD274) expression, and tumor immune microenvironment cell components(TICC)." (PMID 35265072, 2022). "In MES glioma with the highest expression of CHI3L1, CHI3L1 expression was also associated with the level of CD274 (PD-L1)." (PMID 36276655, 2022). "In gliomas of SGMRS high-risk group, the expression levels of CD274 (PD-L1), CD276 (B7-H3), and CD279 (PD-1) were remarkably higher compared to the low-risk group in TCGA cohort." (PMID 36467068, 2022). "Upregulation of some immune checkpoints, such as CD27, CD274 (PD-L1), CTLA4, IDO1, and PDCD1 (PD-1), were reported to be associated with poor survival and recurrence in gliomas." (PMID 35874989, 2022). "B2M exhibited a highly positive correlation with immune checkpoint molecules, such as PDCD1LG2, HAVCR2, CD274 in pan-gliomas and LGG samples, respectively." (PMID 33658560, 2021). "The result showed that ANXA1 and CD274 expression (patient id:122; 3,226) were positive in high grade gliomas, and there is a certain correlation between their expressions." (PMID 34422796, 2021). "In CGGA dataset, PDIA5 expression was positively associated with CD276, CD274, PDCD1LG2, and HAVCR2 in pan-glioma and LGG patients, and positively correlated with CD276, PDCD1, CD274, PDCD1LG2, and HAVCR2 in GBM patients." (PMID 33664747, 2021). "In a database of 674 glioma human samples, mRNA levels of PD-L1(i.e., CD274) were significantly positively correlated to those of PI3K (i.e., PI3KCG) and β-actin (i.e., ACTB), supporting our RNA-sequencing data." (PMID 31850228, 2019). "The qRT-PCR revealed that these regulators were all high-expressed in T98G and DBTRG-05MG, and the depletion of these FRGs could reduce CD274 mRNA expression levels in glioma cells." (PMID 37629061, 2023). "Heatmap and box plots provide a more intuitive and accurate representation, patients with high-risk scores had higher levels of CD274 expression and more malignant glioma pathologic features, regardless of gender." (PMID 37837543, 2023). "The results of qRT-PCR confirmed that these genes were upregulated in glioma cells and could influence the CD274 mRNA expression." (PMID 37629061, 2023). "The gene expression of PDCD1 and CD274 were mainly located in the T cell cluster in glioma." (PMID 37441589, 2023). "The high-risk group presented a higher expression of PD1 (PDCD1), CTLA4, PD-L1 (CD274), and PD-L2 (PDCD1LG2), and our risk signature could also distinguish glioma patients with similar expression levels of immune checkpoints." (PMID 37004060, 2023).